VCL (vinculin)
Diseases named in the same sentence as VCL in open-access papers (continued):
Sharing a sentence is not in itself a finding about the gene and the disease.
melanoma (17 papers, 2011 to 2025). A malignant, usually aggressive tumor composed of atypical, neoplastic melanocytes. "In addition, we found that stimulation of ACE by Ang-II caused the melanoma cells to migrate, at least in part due to decreased vinculin expression, a focal adhesion structural protein." (PMID 27992423, 2016). "Vinculin in the nuclear neighborhood, well-defined actin fibers, and the elongated shape are characteristics of melanoma cells with the mesenchymal phenotype." (PMID 40563555, 2025). "The changes in vinculin expression and FAP and the reduced viability of the melanomas were consistent with regulation of proteins associated with programmed cell death." (PMID 40563555, 2025). "The vinculin delocalization in melanomas with the epithelial cell phenotype led to a significant increase in focal adhesion points at the interphase of the cell membrane and ECM." (PMID 40563555, 2025). "Vinculin delocalization was evident in melanoma cells with both phenotypes 24 h post treatment, yet they exhibited different interactions with actin." (PMID 40563555, 2025). "Localized clusters of vinculin near the nuclei are easily identified in both treated and control melanoma cells exhibiting the epithelial phenotype." (PMID 40563555, 2025). "Vinculin was found to delocalize in the cytoplasm of treated mesenchymal melanoma cells, with a slightly higher concentration at the end of the actin fibers." (PMID 40563555, 2025). "The spatial distribution of vinculin expression is found to be markedly different in the treated melanoma cells compared to the malignant control cells." (PMID 37035583, 2023). "In treated melanoma cells, we found vinculin to be delocalized over the entire cytoplasmic fluid, consistent with an increase in its inactive form, which is consistent with the activation of FAK regulation mechanisms." (PMID 37035583, 2023). "Vinculin stabilizes the actin-FA binding, and its underexpression promotes melanoma motility and metastasis, whereas its activation inhibits tumor growth and sensitizes the tumor to chemotherapy." (PMID 37013489, 2023). "The dispersion is found to deactivate and delocalize vinculin in the first 24 h post-treatment of the melanoma cells." (PMID 37035583, 2023). "Vinculin is found to localize only around the nuclei 48 h post-treatment with a significantly lower expression intensity than that in the corresponding melanoma control." (PMID 37035583, 2023). "Control melanoma cells have significant focal points and vinculin around the nucleus, the latter likely resulting from interactions with talin localized in the cell nucleus." (PMID 37035583, 2023). "The expression of cortactin and vinculin was also analyzed by western immunoblotting in the Mock- or Snail-transfected B16F1 melanoma cells." (PMID 33917849, 2021). "On the other hand, in Snail-B16F1 melanoma cells treated with lumican, vinculin expression is reduced." (PMID 33917849, 2021). "We thus assessed structural organization of actin microfilaments and focal adhesion protein, vinculin, within both melanoma cell lines." (PMID 30242256, 2018). "Images of vinculin and actin expression in these mesenchymal melanomas 24 h post treatment results in delocalization of vinculin in the cytoplasmic fluid and increased colocalization of vinculin and actin, as evidenced by the larger orange area in the composite image." (PMID 40563555, 2025). "Mesenchymal melanoma cells displayed increased vinculin co-localization with actin." (PMID 40563555, 2025). "On the other hand, in Snail-B16F1 melanoma cells treated with lumican, vinculin expression is significantly reduced, leading to the formation of fewer focal adhesions and inhibition of lamellipodia protrusions, further suggesting the anti-metastatic effect of lumican." (PMID 33917849, 2021).
melanoma (continued). "Interestingly, the activation of vinculin sensitized melanoma to chemotherapy and increased adhesion of cells to extracellular matrix ligands, numbers of cell-matrix adhesions, and downstream signaling." (PMID 22905093, 2012). "Interestingly, PMCA4b expression resulted in decreased vinculin expression that might contribute to the reduced migratory activity of the PMCA4b expressing A375 melanoma cells." (PMID 33802790, 2021). "Thus, the role of vinculin in the morphology of the melanoma cells was addressed." (PMID 33917849, 2021). "The CaS dispersions facilitate vinculin delocalization in the cytoplasmic fluid, a result consistent with improved focal adhesion kinase (FAK) regulation in melanoma cells." (PMID 37035583, 2023). "Melanoma cells with the epithelial phenotype exhibit focal-adhesion-bound vinculin, which is not colocalized with actin, in a gradient from the cell membrane to the cytoplasm and immediate outer regions of the nuclei." (PMID 40563555, 2025). "APBB1IP was reported to promote the migration and invasion of melanoma cells 7, and we speculated that APBB1IP might interact with VCL to achieve this function." (PMID 33391455, 2021). "Neither of the vinculin mutants mimicking the constitutively active or inactive form enhanced cell migration in B16F10 melanoma cells." (PMID 25742295, 2015). "To determine whether the FA-stabilizing effect of active vinculin affects cell migration, we tracked the movement of B16F10 melanoma cells." (PMID 23375895, 2013). "In contrast, vinculin staining, which shows that GFP-Nck2 colocalizes with vinculin at focal adhesions, revealed significant reduced number of focal adhesions in human primary melanoma cells overexpressing Nck2 (N14) compared with control melanoma cells (C2)." (PMID 21992144, 2011).
prostate carcinoma (16 papers, 2015 to 2025). A carcinoma that arises from epithelial cells of the prostate gland. "Integrin-linked kinase (ILK), plectin (PLEC), paxillin (PXN), talin 1 (TLN1), and vinculin (VCL) are other adhesome proteins that were implicated in prostate cancer and that showed biomarker potential in this cancer type." (PMID 38255186, 2023). "In addition, vinculin protein levels have been associated with progression in prostate cancer and NSCLC." (PMID 41301074, 2025). "Although larger-scale validation studies involving more patients are still needed, vinculin and galectin-3 seem to be promising urinary biomarker candidates for recurrent prostate cancer, while secernin-1 seems to be a useful tissue diagnostic biomarker candidate for prostate cancer." (PMID 25667921, 2015). "It is reported that Vinculin presents low expression in non-small cell lung cancer, prostate cancer and colon cancer, and is closely related to prognosis." (PMID 36457747, 2022). "Through the application of bioinformatics technology, we identified the potential key genes associated with the occurrence and development of prostate cancer as FGF2, FLNA, VCL, FLNC, CAV1, ACTC1, and MYLK." (PMID 32547947, 2020). "The SRC1 mRNA was significantly downregulated in MCS after 3- and 5-day RPM-exposure of prostate cancer cells, whereas VCL was elevated in MCS in our experimental setting." (PMID 32070055, 2020). "Our TMA analysis also showed that vinculin is significantly upregulated in prostate cancer tissue compared to tumor-free prostatic tissue." (PMID 25667921, 2015). "Vinculin showed high expression levels in 16% of castration-resistant prostate cancer samples and a moderate expression level in 34% of castration resistant prostate cancer samples." (PMID 25667921, 2015). "Prostate tissue samples analyzed by 2D-DIGE (two-dimensional difference in gel electrophoresis) and mass spectrometry (MS) revealed downregulation of secernin-1 (P < 0.044) in prostate cancer, while vinculin showed significant upregulation (P < 0.001)." (PMID 25667921, 2015). "The Western blot analysis of urine confirmed the significant upregulation of vinculin in prostate cancer patients." (PMID 25667921, 2015). "Again, vinculin expression was significantly higher in the urine of prostate cancer patients than in controls (P = 0.006)." (PMID 25667921, 2015). "VCL has been shown to promote tumor progression in GBMs and prostate cancer." (PMID 35563787, 2022). "VCL has been reported as an important prognostic biomarker in prostate cancer." (PMID 36357874, 2022). "Thus vinculin expression and vinculin isoforms in prostate cancer should be analyzed carefully in the future." (PMID 25667921, 2015). "Vinculin was validated as a potential biomarker candidate for recurrent prostate cancer." (PMID 25667921, 2015). "Moreover, vinculin levels were higher in prostate cancer patients' urine (median 0.109 pmol/mg) than in the urine of the control group (median 0.090 pmol/mg)." (PMID 25667921, 2015). "Vinculin levels in Western blots of urine >1 could detect prostate cancer with a sensitivity of 54.2% and a specificity of 85.7%." (PMID 25667921, 2015). "Immunohistochemical vinculin staining could detect prostate cancer with a sensitivity of 38.0% and a specificity of 56.9% for a threshold score ≤1 versus >1." (PMID 25667921, 2015). "In 92% of the localized prostate cancer samples, vinculin showed a low expression level." (PMID 25667921, 2015). "Moreover, vinculin showed higher protein levels in the urine of prostate cancer patients with recurrence compared to the urine from patients without recurrence." (PMID 25667921, 2015). "These two studies showed that different vinculin isoforms may be differentially expressed in prostate cancer." (PMID 25667921, 2015). "Moreover, this supports the hypothesis that its interaction with vinculin is an adaptive mechanism to protect μg-exposed prostate cancer cells and other cell types." (PMID 32070055, 2020).
prostate carcinoma (continued). "Most importantly, vinculin levels in urine from prostate cancer patients with relapse were higher than in urine from patients without relapse (median score without relapse 1.00; median with relapse 1.75; P = 0.229; median vinculin score in the control urine 0.250; P = 0.006)." (PMID 25667921, 2015). "Thus, future analysis of a larger number of patient samples may validate the potential of vinculin as a biomarker candidate for recurrent prostate cancer." (PMID 25667921, 2015). "Currently, quantitative proteomics has identified VCL and FLNC as two potential prognostic biomarkers and therapeutic targets for prostate cancer cell migration." (PMID 32547947, 2020). "In prostate cancer (PCa), small EVs have been reported to contain high levels of molecules that stimulate cancer cell invasion, such as integrins β4 (ITGB4) and αvβ6, vinculin (VCL), transmembrane glycoprotein Trop-2, vimentin, and N-cadherin, well-known epithelial–mesenchymal transition markers." (PMID 29951374, 2018). "Vinculin expression has been shown to be upregulated in prostate cancer patient tissue samples, while the urine of recurrent prostate cancer patients showed higher vinculin levels than nonrecurrent prostate cancer patients." (PMID 25667921, 2015). "Urinary vinculin levels in prostate cancer patients were significantly higher than in urine from nontumor patients (P = 0.006)." (PMID 25667921, 2015). "Our 2D-DIGE analysis showed that vinculin abundance is higher in recurrent prostate cancer compared to nonrecurrent prostate cancer tissue." (PMID 25667921, 2015). "In the MRM-MS analysis of vinculin, 16 prostate cancer patients (nine without relapse and seven with relapse) and seven control urine samples were used." (PMID 25667921, 2015).
cardiomyopathy (15 papers, 2010 to 2025). A disease of the heart muscle or myocardium proper. "Loss of αE-catenin from the mouse heart disrupts AJ formation and causes a marked decrease in vinculin expression and recruitment, despite the presence of αT-catenin, resulting in cardiomyopathy." (PMID 33771561, 2021). "Both ALPK3 and VCL are associated with cardiomyopathy, and CAND2 is associated with atrial fibrillation and also creatine kinase concentrations." (PMID 33961016, 2021). "Vinculin (VCL) was linked to sudden arrhythmia death in VCL knockout mice prior to the appearance of cardiomyopathy." (PMID 28218286, 2017). "Others have reported linkage of multiple mutations of VCL with dilated and hypertrophic forms of human cardiomyopathy." (PMID 27635260, 2016). "The VCL-encoding protein was involved in cardiomyopathy that associated with hypertension, therefore our results suggest the rs4746172 of VCL may be a novel target for clinical interventions to reduce CVD risk by regulating blood pressure in male Chinese." (PMID 26487440, 2015). "This may imply either recovered DCM in the parent, or that VCL variants may be genetic modifiers in the context of other genetic or environmental factors.We did not identify fetal or postnatal insults or other pathogenic genetic variants that could contribute to cardiomyopathy." (PMID 37548861, 2023). "The cardiac-specific VCL knockdown resulted in early development of ventricular tachycardia followed by cardiomyopathy and all mice died before 6 months of age." (PMID 27635260, 2016). "Numerous sarcomeric components/cytoskeletal proteins were identified as showing increased synthesis in our pSILAC experiments, several of which play important roles in cardiac function and/or in cardiomyopathies (e.g. desmin, vinculin, NRAP (nebulin-related anchoring protein) and Lmod)." (PMID 27512079, 2016). "It allowed us to capture the evolving cardiomyopathy phenotype unlike previous cross-sectional studies that may have missed an earlier diagnosis of DCM in recovered older patients resulting in the perception of reduced penetrance of VCL variants." (PMID 37548861, 2023). "Furthermore, vinculin appears important in neuronal cell motility and contractility and cardiac formation, as evidenced by the neural tube, myocardial and endocardial defects in vinculin knockout mice, as well as stress-induced cardiomyopathy in heterozygous mutants." (PMID 25970536, 2015). "VCL p.(Gly812Ala), a novel variation that has never been reported, was found in a 51-year-old female suffering from cardiomyopathy dilated with sustained ventricular tachycardia." (PMID 39940965, 2025). "This helped us identify differences in variant burden by cardiomyopathy type in not only sarcomere but also non-sarcomere genes e.g., OBSCN was enriched for variants in adults, while VCL was more frequently mutated in children." (PMID 37477868, 2023).
heart failure (11 papers, 2013 to 2025). Inability of the heart to pump blood at an adequate rate to meet tissue metabolic requirements. "Here, we describe a unique phenotype of heart failure with reduced ejection fraction (HFrEF) that evolves to HF with recovered ejection fraction (HFrecEF) in DCM patients with VCL LOF variants." (PMID 37548861, 2023). "Vinculin is a costametric protein in cardiomyocytes, and vinculin overexpression in myocardium was reported to be associated with aging and heart failure." (PMID 36135831, 2022). "The integrin-like protein vinculin is reportedly associated with heart failure in humans, and carriers of vinculin missense mutation are more sensitive to HF." (PMID 27904993, 2017). "For example, missense mutations in vinculin encoding integrin-like protein are associated with an increased incidence of heart failure in humans, whereas cardiac overexpression of vinculin in flies positively influences heart performance and increases lifespan." (PMID 34831301, 2021). "Vinculin overexpression has been associated with focal adhesion complex formation at the site of integrin binding and may have implications in the transmission of contractile forces and in heart failure." (PMID 40725013, 2025). "As shown here, in cardiomyocytes, targeted ablation of Paxillin also led to the mislocalization of Vinculin, its destabilization and subsequent degradation resulting in heart failure in zebrafish." (PMID 26954676, 2016). "Furthermore, we recently found that targeted inactivation of Vinculin in zebrafish also leads to severe contractile dysfunction and heart failure in vivo." (PMID 26954676, 2016). "However, we further demonstrate here that Paxillin-mediated heart failure is caused by the destabilization of the interaction partners Paxillin and FAK, leading to impaired recruitment and subsequent degradation of Vinculin." (PMID 26954676, 2016). "However, we found that Paxillin deficiency leads to the destabilization of its known binding partner Focal Adhesion Kinase (FAK) and vice versa resulting in degradation of Vinculin and thereby heart failure." (PMID 26954676, 2016). "The levels of this protein are reported to increase along with other cytoskeletal proteins such as tubulin, vinculin and vimentin under conditions of idiopathic dilated cardiomyopathy and also during transition from compensated ventricular hypertrophy to heart failure." (PMID 23706090, 2013). "Absence of both, FAK and Vinculin is associated with heart failure in mice and humans." (PMID 26954676, 2016).
glioma (10 papers, 2008 to 2024). A benign or malignant brain and spinal cord tumor that arises from glial cells (astrocytes, oligodendrocytes, ependymal cells). "FOCAD protein was first described to be encoded by KIAA1797 gene as a novel component of the focal adhesion complex to co-localize and interact with vinculin in glioma cells." (PMID 34685504, 2021). "Similarly, in vitro studies have shown an upregulation of focal adhesion proteins, such as FAK and Vinculin, and a faster migration of glioma cells in oversulfated hydrogel matrices when compared to nonsulfated hydrogels." (PMID 36980765, 2023).
lung carcinoma (10 papers, 2013 to 2025). "In A549 cell line, the NME2 downregulation causes transcriptional de-repression of vinculin, thus promoting lung cancer metastasis." (PMID 34628473, 2021). "To begin to understand the clinical relevance of alterations in vinculin protein levels in relation to lung cancer survival, we examined Kaplan plots generated from TCGA data." (PMID 29899821, 2018). "To assess the clinical relevance of these findings, we wondered if vinculin mRNA or protein levels in patient samples correlate with lung cancer survival." (PMID 29899821, 2018). "Together, we demonstrate that reduced NME2 levels lead to transcriptional de-repression of vinculin and regulate lung cancer metastasis." (PMID 25249619, 2014). "Therefore, a decreased expression of NME2 in lung cancer led to enhanced transcription of vinculin and an increase in cell migration and invasion." (PMID 39063217, 2024). "Importantly, to validate our observation in different lung cancer lines, we found increased vinculin levels upon NME2 knockdown in H157 cells, another non-small cell lung carcinoma line." (PMID 25249619, 2014). "In addition, knockdown of Nm23-H1 also altered the polymerization of actin and increased the protein levels of EMT-related proteins, fibronectin, N-cadherin, vimentin, phospho-FAK and vinculin, implying that a decrease in Nm23-H1 increases the invasive ability of lung cancer cells." (PMID 28831131, 2017). "In lung cancer, NME2 regulates focal adhesion function through its binding to the vinculin promoter, inducing a decrease in vinculin expression at the RNA and protein level." (PMID 39063217, 2024). "We also found several recurrent ALK fusions which have not been reported in lung cancer, but have been identified in other cancer types, such as VCL-ALK, FN1-ALK, and NPM1-ALK." (PMID 34508169, 2021). "Whereas information on vinculin protein levels and lung cancer survival is still lacking, information on vinculin mRNA levels and lung cancer survival is available from TCGA database." (PMID 29899821, 2018).